RPS4Y2 (ribosomal protein S4 Y-linked 2)
Synonyms: RPS4Y2P
Tractability: PROTAC: ubiquitination databases record sites on it.
Gene: Protein-coding gene on chromosome Y (20,756,108 to 20,781,032, forward strand). Ensembl gene ENSG00000280969.
Pathways (Reactome):
Metabolism of proteins: Eukaryotic Translation Termination; Formation of a pool of free 40S subunits; Formation of the ternary complex, and subsequently, the 43S complex; GTP hydrolysis and joining of the 60S ribosomal subunit; L13a-mediated translational silencing of Ceruloplasmin expression; PELO:HBS1L and ABCE1 dissociate a ribosome on a non-stop mRNA; Peptide chain elongation; Ribosomal scanning and start codon recognition; SRP-dependent cotranslational protein targeting to membrane; Translation initiation complex formation; ZNF598 and the Ribosome-associated Quality Trigger (RQT) complex dissociate a ribosome stalled on a no-go mRNA
Disease: SARS-CoV-1 modulates host translation machinery; SARS-CoV-2 modulates host translation machinery; Viral mRNA Translation
Metabolism of RNA: Major pathway of rRNA processing in the nucleolus and cytosol; Nonsense Mediated Decay (NMD) enhanced by the Exon Junction Complex (EJC); Nonsense Mediated Decay (NMD) independent of the Exon Junction Complex (EJC)
Cellular responses to stimuli: Response of EIF2AK4 (GCN2) to amino acid deficiency
Developmental Biology: Regulation of expression of SLITs and ROBOs
Metabolism: Selenocysteine synthesis
Gene Ontology:
Molecular function: RNA binding; structural constituent of ribosome
Biological process: translation
Cellular component: cytosolic small ribosomal subunit; ribosome
Homologues: Orthologues: chimpanzee RPS4Y2 (97% identical), macaque RPS4Y2 (95% identical), tropical clawed frog rps4x (92% identical), zebrafish rps4x (87% identical), Drosophila melanogaster RpS4 (71% identical), Caenorhabditis elegans rps-4 (60% identical). Paralogues in human: RPS4Y1 (94% identical), RPS4X (92% identical).
Diseases named in the same sentence as RPS4Y2 in open-access papers:
RPS4Y2 is named in the same sentence as 5 diseases in open-access papers, as found by Europe PMC text mining. Sharing a sentence is not in itself a finding about the gene and the disease. The quoted sentences say what the papers report.
Infertility (1 paper, 2010). "Therefore, it is plausible that deficits in specific ribosomal proteins may have some bearing on infertility or subfertility phenotypes, to which the particular contribution of RPS4Y2 should be further explored." (PMID 20459660, 2010).
male infertility (1 paper, 2010). The inability of the male to effect fertilization of an ovum after a specified period of unprotected intercourse. "Moreover RPS4Y2 has acquired an exclusive expression pattern that suggests that it may have a role in germ cell development and its location within the AZFb region makes it a good candidate for male infertility." (PMID 20459660, 2010).
cancer (1 paper, 2025). A tumor composed of atypical neoplastic, often pleomorphic cells that invade other tissues. "Here, we found nonsynonymous variants impacting AMELY, DDX3Y, RPS4Y2, and TBL1Y in five African tumors (4.7%), and UTY in a single European tumor (1.8%), highlighting the potential for these chrY genes as ancestry-specific cancer driver candidates." (PMID 40454088, 2025).
tumor (1 paper, 2025). "Nonsynonymous mutations were found in the genes AMELY, DDX3Y, RPS4Y2, TBL1Y in African tumors (5 samples: 4 HRPCa 1 LRPCa), and in UTY in one European HRPCa tumor." (PMID 40454088, 2025).
RPS4Y2 also shares sentences with these, for which no sentence is quoted: Azoospermia (2 papers).